RNU6-386P (RNA, U6 small nuclear 386, pseudogene)
Gene: Small nuclear RNA gene on chromosome 3 (77,092,057 to 77,092,163, forward strand). Ensembl gene ENSG00000199520.
Homologues: Orthologues: chimpanzee U6 (96% identical), macaque U6 (93% identical), pig U6 (81% identical), mouse Gm24762 (79% identical). Paralogues in human: RNU6-1331P (85% identical), RNU6-166P (83% identical), RNU6-727P (83% identical), RNU6-1091P (82% identical), RNU6-11P (82% identical), RNU6-1274P (82% identical), RNU6-1287P (82% identical), RNU6-15P (82% identical), RNU6-242P (82% identical), RNU6-28P (82% identical), RNU6-37P (82% identical), RNU6-43P (82% identical), and 1284 more.